IL9R (interleukin 9 receptor)
Diseases named in the same sentence as IL9R in open-access papers (continued):
Sharing a sentence is not in itself a finding about the gene and the disease.
unstable angina (1 paper, 2013). "These new findings further underscore a link between IL-9 and IL-17 and suggest that this link is particularly strong in patients with unstable angina, potentially reflecting up-regulation of IL-9R in T cells from these patients." (PMID 24023645, 2013). "To further examine the regulation of IL-9 in atherosclerotic disorders, we analyzed mRNA levels of IL-9 and IL-9R in T cells and monocytes from patients with stable and unstable angina and in healthy controls." (PMID 24023645, 2013). "Finally, enhanced expression was also seen at the cellular level with increased levels of IL-9 mRNA and IL-9R in T cells from patients with unstable angina, and for IL-9, this up-regulation was also seen in monocytes." (PMID 24023645, 2013). "T cells from patients with unstable, but not stable angina had significantly increased mRNA expression of IL-9 and IL-9R compared with T cells from healthy controls, and for IL-9, the difference between unstable and stable disease was also significant." (PMID 24023645, 2013).
vaginal candidiasis (1 paper, 2018). "We next evaluated the susceptibility of Il9R−/− mice to vaginal candidiasis." (PMID 30515173, 2018).
tumor (22 papers, 2016 to 2025). "IL-9R-deficient tumor-bearing mice exhibited lower serum IL-6 level than WT mice." (PMID 35778404, 2022). "Because the IL-9/IL-9R axis is important for reducing lipid peroxidation and ferroptosis in Tc9 cells in vitro, we investigated whether IL-9 or IL-9R deficiency could affect the Tc9 cells’ ability to persist and control tumor growth in vivo." (PMID 35192544, 2022). "Conversely, IL-9 can support tumor growth in IL-9R-expressing malignancies, including lymphomas, lung cancer and pancreatic cancer." (PMID 41030439, 2025). "IL-9 can also act directly on tumor cells expressing IL-9R, such as squamous cancer (SqC) cells and cervical cancer, to directly kill these tumor cells." (PMID 36936961, 2023). "IL-9 has opposing effects on IL-9R-positive tumor cells: from cytostatic and cytotoxic effects to promoting tumor cell growth and migration." (PMID 37189417, 2023). "The fact that Arg1-expressing macrophages can rescue tumor growth in Il9r−/− mice indicates Arg1 is a critical effector in IL-9-macrophage mediated tumor growth." (PMID 35778404, 2022). "As these findings suggested the possibility that IL-9 induces IL-9R expression in intestinal epithelial cells, we next determined the functional effects of IL-9 signalling on IL-9R expression by in vitro studies using tumour organoids." (PMID 35793807, 2022). "We sorted lung AMs, CD11c+ and CD11c− IMs from WT Boy/J (CD45.1+) tumor bearing mice and then transferred them to Il9r−/− mice (CD45.2+) 4 days after tumor cell injection." (PMID 35778404, 2022). "While IL-9 alone was not sufficient to induce tumor migration, macrophages from both WT and Il9r−/− mice promoted tumor migration to a similar extent." (PMID 35778404, 2022). "Here, the authors show that IL-9 promotes the expansion of pulmonary macrophages and that targeting the IL-9R/arginase 1 axis restricts tumor growth, thus identifying this cytokine pathway as a potential therapeutic target." (PMID 35778404, 2022). "Mice that received WT macrophages showed more tumor growth than mice that received Il9r−/− macrophages." (PMID 35778404, 2022). "In each of the tumor models, Il9r−/− mice also showed significantly lower arginase activity than WT mice, indicating differential expression is related to function." (PMID 35778404, 2022). "Compared with macrophages within normal lung tissue, macrophages located in the tumor site expressed dramatically more IL-9R." (PMID 35778404, 2022). "To understand how IL-9 signaling affects the transcriptional landscape of lung macrophages, we compared the gene expression of WT and Il9r−/− macrophages from intact lungs of tumor-bearing mice." (PMID 35778404, 2022). "In fact, we noted here that IL-9 controls tumor cell growth in NSCLC via direct effects on IL-9R expressing cancer cells." (PMID 35514957, 2022). "To explore if the regulatory pattern of IL-9 on macrophages is also consistent in other tumor environments, we also assessed IL-9R in a B16 s.c. model." (PMID 35778404, 2022). "Flow cytometry analysis clearly showed an upregulation of IL-9R expression in the tumour tissue of wild-type and IL-9 knockout mice as compared with control tissue lacking tumours." (PMID 35793807, 2022). "Lung macrophage populations demonstrated a similar pattern as the results from i.v. injection tumor models: increased AM and decreased CD11c+ and CD11c− IM in Il9r−/− mice." (PMID 35778404, 2022). "Immunofluorescence staining for IL-9R confirmed expression on epithelial cells of tumour tissue in wild-type mice." (PMID 35793807, 2022). "Compared to control mice, Il9fl/fl CD4-Cre+ mice showed less tumor growth and decreased IM populations, similar to the pattern observed in Il9r−/− mice." (PMID 35778404, 2022). "IL-9R−/− mice show increased tumor growth, while, on the other hand, injection of recombinant mouse IL-9 into melanoma-bearing mice inhibits tumor growth." (PMID 34944921, 2021).
tumor (continued). "TH9-derived IL-9 leads to upregulation of p21 and TRAIL, thus inducing tumor cell cycle arrest and apoptosis upon activation of IL-9R." (PMID 27832300, 2017). "In our previous study, immunohistochemical analysis showed that the IL-9R protein was located on the membrane of tumor cells within DLBCL tissues." (PMID 27364124, 2016). "Malignant DLBCL cells in tissue sections were confirmed by pathologists, and IL-9R was located on the surface of these tumor cells." (PMID 27364124, 2016). "Currently, the role of tumor-specific IL-9R expression on Th9-mediated anti-tumor immunity in vivo remains unclear." (PMID 41030439, 2025). "These dual roles underscore the importance of tumor-intrinsic IL-9R expression and the tumor microenvironment in determining whether IL-9 promotes or inhibits tumor growth." (PMID 41030439, 2025). "T cells expressing a chimeric receptor containing the extracellular domain of IL-2R fused with the intracellular domain of IL-9R acquire features of effector T cells and show anti-tumor activity when adoptively transferred in syngeneic mouse models of melanoma and pancreatic cancer." (PMID 39281678, 2024). "Moreover, neutralizing anti-IL-9 or anti-IL-9R antibodies significantly inhibit tumor growth in mouse models of lymphoma." (PMID 39281678, 2024). "However, IL-9R knockdown in CMT167 cells abrogated the IL-9-driven tumor growth inhibition and enhanced T-cell infiltration." (PMID 37189417, 2023). "Arg1fl/flLysM-Cre− IMs, but not Arg1fl/flLysM-Cre+ IMs, rescued the loss of tumor growth in Il9r−/− mice." (PMID 35778404, 2022). "IL-9 target cells in NSCLC consisted of IL-9R+ tumor cells and tumor-infiltrating lymphocytes." (PMID 35514957, 2022). "Similar to tumor growth in the B16 i.v injection model, the Il9r−/− mice showed less tumor growth." (PMID 35778404, 2022). "Although the precise reasons for these differences remain currently unclear, they may be related to the specific microenvironment provided by lung TILs in NSCLC or to the question whether the targeted tumor cell type expresses the IL-9R." (PMID 35514957, 2022). "Therefore, by repurposing IL-9R signalling using a chimeric orthogonal cytokine receptor, T cells gain new functions, and this results in improved anti-tumour activity for hard-to-treat solid tumours." (PMID 35676488, 2022). "As expected, tumor-infiltrating Il9–/– or Il9r–/– Tc9 cells had higher lipid peroxidation and cellular iron levels, and lower mitochondrial activity than WT Tc9 cells, indicating that IL-9– or IL-9 signaling–deficient Tc9 cells undergo enhanced ferroptosis in the TME." (PMID 35192544, 2022). "Moreover, they showed that neutralizing anti-IL-9 or anti-IL-9R antibodies significantly inhibit tumor growth in mouse models of lymphoma." (PMID 34944921, 2021). "Specifically, although in a few cases, IL9R is only expressed in the tumor cells." (PMID 33329510, 2020). "Additionally, IL-9R−/− mice showed increased tumor growth, and the injection of rmIL-9 into melanoma-bearing mice inhibited tumor growth." (PMID 32228589, 2020). "In addition, melanoma tumor growth is accelerated in IL-9R−/− mice, and treatment with rIL-9 inhibited this growth." (PMID 27589682, 2016). "Similarly, Il9r(−/−) mice displayed accelerated tumor growth." (PMID 41148223, 2025). "To explore whether the macrophages themselves lead to altered tumor growth between WT and Il9r−/− mice, or whether the crosstalk between the microenvironment and the lung macrophages were the major driver, we employed a lung macrophage adoptive transfer experiment in the tumor model." (PMID 35778404, 2022). "Therefore, higher levels of IL9R might contribute to anti-tumor effects through cytotoxic effector T cells and a shifting towards a favorable ICI response." (PMID 36551692, 2022). "However, mostly, IL9R was not only detected in tumor cells but also infiltrated lymphocytes." (PMID 33329510, 2020).
tumor (continued). "However, IL-9R expression is increased in EL-4 cells, indicating an additional effect of IL-9 on tumor cells; evaluation of IL-9R expression may therefore be critical for IL-9 anti-tumor therapy." (PMID 27589682, 2016). "By contrast, these tumours lack the typical markers for GATA3+ PTCL‐NOS such as Il2ra, il9r, and Gata3 itself." (PMID 35895495, 2022). "Additionally, they could be due to certain differences in the IL-9R expression on tumour cells." (PMID 35793807, 2022). "To determine whether this concept is also relevant for tumor cells and TILs in NSCLC patients, we next assessed the distribution of IL-9R in patient samples." (PMID 35514957, 2022). "While it is possible AMs contribute to the IL-9-dependent tumor promoting phenotype in early tumor development, we did not observe significant changes of AM numbers comparing WT and Il9r−/− mice." (PMID 35778404, 2022). "In contrast, mice lacking mast cells, which express moderate levels of IL-9 in INFER mice, have increased tumor growth and did not have the same changes in macrophage populations observed when IL-9 or IL-9R are lost." (PMID 35778404, 2022). "To assess the role of IL-9 in the antitumor effects of FasL-TH9, we intravenously or subcutaneously challenged Il9r−/− mice with B16F10-OVA tumor cells and found that neither FasL-TH9 nor cTH9 enhanced antitumor immunity." (PMID 31266950, 2019). "We observed an induction of IL-9 production by tumor infiltrating lymphocytes (TIL) and a subset of FoxP3+ regulatory T cells in the tumoral region of NSCLC patients and identified tumor infiltrating T cells, FoxP3+ Treg cells and tumor cells as IL-9R expressing target cells for IL-9 signaling." (PMID 35514957, 2022). "Interestingly, TAMs in the s.c. tumor model did not express IL-9R compared to isotype control staining sample." (PMID 35778404, 2022). "Interestingly, the TAMs in the s.c.B16 tumor do not express IL-9R, which suggests the ability of IL-9 to regulate macrophages could be organ-specific or dependent on the local microenvironment." (PMID 35778404, 2022). "Strikingly, YFP+ (i.e. Arg1+) macrophages successfully recused tumor growth in Il9r−/− mice, while YFP- macrophages did not promote tumor growth." (PMID 35778404, 2022). "To elucidate the role of IL-9 in the antitumor effects of these cells, we subcutaneously challenged Il9r−/− mice with B16F10-OVA tumor cells and found that neither FasL + p38i-TH9 nor FasL-TH9 could inhibit tumor progression." (PMID 31266950, 2019).
cancer (6 papers, 2020 to 2024). A tumor composed of atypical neoplastic, often pleomorphic cells that invade other tissues. "Gene set enrichment analysis between WT and Il9r−/− CD11c+ or CD11c− IMs identified changes in reactive oxygen species pathways and cancer module pathways." (PMID 35778404, 2022). "Based on these findings, we further explored the therapeutic efficacy of targeting IL-9R signaling in lung macrophages for cancer therapy." (PMID 35778404, 2022). "Cancer cells modulate the expression and secretion of several anti-proliferative molecules on DBMSCs, including, CD40LG, CXCL9, IL9R, IL-15, TNFSF13B, IL-9, IL-17, and CXCL1." (PMID 39768220, 2024). "We also revealed six oncogenes that have been validated to be related to the poor prognosis of patients with cancer: CTSE, CALM1, PHGDH, IL9R, and CD96." (PMID 35433683, 2022).
infection (5 papers, 2017 to 2025). The state of being infected such as from the introduction of a foreign agent such as serum, vaccine, antigenic substance or organism. "As compared to C57BL/6, Il9R−/− mice showed a reduced inflammation in the initial phase of infection, but an increased susceptibility in a later phase, as indicated by fungal burden, inflammatory cell recruitment in the vaginal fluids and mucosa and IL-1β production." (PMID 30515173, 2018). "This turned out to be the case as Il1Ra was down-regulated in Il9R−/− mice at 14 days post-infection." (PMID 30515173, 2018). "IL-9R-deficient mice on both, BALB/c and C57BL/6 genetic background displayed (i) increased and prolonged parasite burden in the small intestine; (ii) reduced early degranulation of mucosal mast cells; (iii) reduced intestinal IL-13 expression and (iv) complete protection against a second infection." (PMID 29872093, 2018). "The expression of Il9 increased early and was observed throughout the infection in C57BL/6 mice, but was unaffected in Il9R−/− mice, a finding suggesting that IL-9 expression is IL-9R-dependent." (PMID 30515173, 2018). "Conversely, in Il9R−/− mice, the IL-22/NLRC4 axis was not only maximally induced but also maintained throughout the infection." (PMID 30515173, 2018). "To test the quality of the adaptive immune response that was initiated in the absence of IL-9R in a more stringent approach, we measured the immune-mediated protection against a second infection." (PMID 29872093, 2018). "Although the absence of IL-9R-mediated signalling modulated T and B cell responses during infection to some extent, functional IL-9R was not essential for the establishment of protective immune memory against a second S. ratti infection." (PMID 29872093, 2018). "Peak production of IL-9 was also observed in Rag1−/−, and less in Rag1−/−/Il9R−/−, mice early but not late in infection, a finding suggesting that early IL-9 production is IL-9R-dependent and late is T-cell-dependent." (PMID 28090087, 2017). "Importantly, our results indicate that the effects of 4-1BB stimulation are dependent on interleukin (IL)-9R signaling in B cells but independent of parasite load during primary infection." (PMID 40215168, 2025). "We provide evidence that this delayed activation of IL-9R−/− mast cells did not reflect intrinsic functional defects independent of the infection context because WT and IL-9R−/− mast cells responded equally well to FcR-mediated stimulation with model antigens or S. ratti-derived antigens in vitro." (PMID 29872093, 2018).
IL9R also shares sentences with these, for which no sentence is quoted: leukemia (2 papers); lung disease (2); acute pancreatitis (1); acute T cell leukemia (1); adenocarcinoma (1); atopic dermatitis (1); cutaneous T cell lymphoma (1); dilated cardiomyopathy (1); mantle cell lymphoma (1); megakaryoblastic leukemia (1); ovarian carcinoma (1); periodontitis (1); renal carcinoma (1); schizophrenia (1); Stroke (1); T-cell leukemia (1).